LITATS1 (lncRNA induced by TGF-beta and antagonizes TGF-beta signaling 1)
Synonyms: LOC728431; LINC01137; ZC3H12A-DT
Gene: Long non-coding RNA gene on chromosome 1 (37,333,698 to 37,474,432, reverse strand). Ensembl gene ENSG00000233621.
Diseases named in the same sentence as LITATS1 in open-access papers:
LITATS1 is named in the same sentence as 5 diseases in open-access papers, as found by Europe PMC text mining. Sharing a sentence is not in itself a finding about the gene and the disease. The quoted sentences say what the papers report.
cancer (2 papers, 2023). A tumor composed of atypical neoplastic, often pleomorphic cells that invade other tissues. "Ectopically expressed LITATS1 proficiently inhibited TGFβ-induced migration of cancer cells, whereas LITATS1-depleted MDA-MB-231 cancer cells demonstrated a notable increase in TGFβ-induced migration." (PMID 37568787, 2023).
LITATS1 also shares sentences with these, for which no sentence is quoted: tumor (2 papers); endometrial cancer (1); myeloid leukemia (1); psoriasis (1).